GALNT15 (polypeptide N-acetylgalactosaminyltransferase 15)
Description:
Catalyzes the initial reaction in O-linked oligosaccharide biosynthesis, the transfer of an N-acetyl-D-galactosamine residue to a serine or threonine residue on the protein receptor. Although it displays a much weaker activity toward all substrates tested compared to GALNT2, it is able to transfer up to seven GalNAc residues to the Muc5AC peptide, suggesting that it can fill vicinal Thr/Ser residues in cooperation with other GALNT proteins. Prefers Muc1a as substrate.
Synonyms: GALNTL2; GALNT7; pp-GalNAc-T15; GALNACT15; PIH5
Tractability: Antibody: UniProt predicts a signal peptide or a membrane-spanning region.
Gene: Protein-coding gene on chromosome 3 (16,174,573 to 16,231,992, forward strand). Ensembl gene ENSG00000131386.
Subcellular location: Golgi apparatus membrane
Subcellular location (Human Protein Atlas): Golgi apparatus; Cytosol
Pathways (Reactome):
Metabolism of proteins: O-linked glycosylation of mucins
Gene Ontology:
Molecular function: protein binding; polypeptide N-acetylgalactosaminyltransferase activity
Biological process: protein O-linked glycosylation; protein O-linked glycosylation via N-acetyl-galactosamine
Cellular component: transport vesicle; Golgi apparatus; Golgi membrane
Genetic constraint (gnomAD): Loss-of-function variants: 64 observed, 70.49 expected, observed/expected ratio (o/e) 0.91, 90% interval 0.74 to 1.12. The upper end of that interval is the gene's LOEUF score, 1.12, which puts it in group 4 of 6, group 1 being the genes least tolerant of losing a copy. Missense variants: 809 observed, 826.96 expected, observed/expected ratio (o/e) 0.98, 90% interval 0.92 to 1.04. Synonymous variants: 303 observed, 320.26 expected, observed/expected ratio (o/e) 0.95, 90% interval 0.86 to 1.04.
Homologues: Orthologues: chimpanzee GALNT15 (99% identical), macaque GALNT15 (96% identical), dog GALNT15 (87% identical), pig GALNT15 (83% identical), guinea pig GALNT15 (81% identical), rat Galnt15 (79% identical), mouse Galnt15 (78% identical), rabbit GALNT15 (75% identical), tropical clawed frog galnt15 (47% identical), Drosophila melanogaster Pgant5 (30% identical), Caenorhabditis elegans gly-10 (29% identical), Caenorhabditis elegans gly-5 (29% identical), and 10 more. Paralogues in human: GALNT12 (37% identical), GALNT4 (34% identical), GALNT6 (32% identical), GALNT3 (32% identical), GALNT10 (31% identical), GALNT5 (30% identical), GALNT13 (30% identical), GALNTL6 (30% identical), GALNT1 (29% identical), GALNT11 (29% identical), GALNT2 (29% identical), GALNT16 (28% identical), and 7 more.
Diseases named in the same sentence as GALNT15 in open-access papers:
GALNT15 is named in the same sentence as 6 diseases in open-access papers, as found by Europe PMC text mining. Sharing a sentence is not in itself a finding about the gene and the disease. The quoted sentences say what the papers report.
gastric cancer (1 paper, 2025). A primary or metastatic malignant neoplasm involving the stomach. "Interestingly, high expression of GALNT15, one of 3 genes in GRGM-3, was recently shown to predict poor outcomes in gastric cancer patients, and associated with pro-tumorous immune cell infiltration." (PMID 40927708, 2025).
glioma (1 paper, 2024). A benign or malignant brain and spinal cord tumor that arises from glial cells (astrocytes, oligodendrocytes, ependymal cells). "Another upregulated gene, GALNT15 has been previously shown to be upregulated in low grade glioma." (PMID 38428408, 2024).
Obesity (1 paper, 2024). Accumulation of substantial excess body fat. "Our findings suggest that GALNT15 is an attractive drug target for the treatment of obesity." (PMID 39209927, 2024).
tumor (1 paper, 2025). "However, it is currently unclear how GALNT15 or other glycan-related factors affect tumor immune-microenvironment, and whether they can serve as biomarkers to predict patient response to immunotherapy." (PMID 40927708, 2025).
GALNT15 also shares sentences with these, for which no sentence is quoted: alcoholic fatty liver disease (1 paper); cervical cancer (1).